HYPK (huntingtin interacting protein K)
Description:
Component of several N-terminal acetyltransferase complexes. Inhibits the N-terminal acetylation activity of the N-terminal acetyltransferase NAA10-NAA15 complex (also called the NatA complex). Has chaperone-like activity preventing polyglutamine (polyQ) aggregation of HTT in neuronal cells probably while associated with the NatA complex. May play a role in the NatA complex-mediated N-terminal acetylation of PCNP.
Synonyms: C15orf63; HSPC136; FLJ20431
Tractability: Small molecule: a structure with a bound ligand is known. PROTAC: ubiquitination databases record sites on it; its protein half-life has been measured.
Gene: Protein-coding gene on chromosome 15 (43,796,142 to 43,804,574, forward strand). Ensembl gene ENSG00000242028.
Subcellular location: Nucleus; Cytoplasm
Subcellular location (Human Protein Atlas): Nucleoplasm; Microtubules
Gene Ontology:
Molecular function: protein binding; protein folding chaperone
Biological process: negative regulation of apoptotic process; protein stabilization; protein folding
Cellular component: cytoplasm; nucleoplasm; nucleus; protein-containing complex
Genetic constraint (gnomAD): Loss-of-function variants: 9 observed, 14.83 expected, observed/expected ratio (o/e) 0.61, 90% interval 0.37 to 1.06. The upper end of that interval is the gene's LOEUF score, 1.06, which puts it in group 4 of 6, group 1 being the genes least tolerant of losing a copy. Missense variants: 138 observed, 167.34 expected, observed/expected ratio (o/e) 0.82, 90% interval 0.72 to 0.95. Synonymous variants: 76 observed, 61.41 expected, observed/expected ratio (o/e) 1.24, 90% interval 1.03 to 1.5.
Homologues: Orthologues: chimpanzee HYPK (100% identical), macaque HYPK (100% identical), mouse Hypk (100% identical), pig HYPK (100% identical), rabbit HYPK (100% identical), rat Hypk (100% identical), guinea pig HYPK (98% identical), tropical clawed frog hypk (88% identical), zebrafish hypk (87% identical), dog HYPK (79% identical), Drosophila melanogaster CG9922 (46% identical), Caenorhabditis elegans F13G3.10 (28% identical).
Diseases named in the same sentence as HYPK in open-access papers:
HYPK is named in the same sentence as 4 diseases in open-access papers, as found by Europe PMC text mining. Sharing a sentence is not in itself a finding about the gene and the disease. The quoted sentences say what the papers report.
Huntington disease (3 papers, 2014 to 2020). Huntington disease (HD) is a rare neurodegenerative disorder of the central nervous system characterized by unwanted choreatic movements, behavioral and psychiatric disturbances and dementia. "HYPK (Huntingtin Yeast Partner K) was originally identified by yeast two-hybrid assay as an interactor of Huntingtin, the protein mutated in Huntington's disease." (PMID 24465598, 2014). "Das found that heat stress induces Huntington’s disease in mice, and HYPK (Huntingtin Yeast Partner K) could alleviate huntington’s reaction by suppressing the heat shock response." (PMID 32787853, 2020).
cardiovascular disorder (1 paper, 2025). A disease involving the cardiovascular system. "HYPK, acting as a regulator of the heat shock response – an important mechanism in other cardiovascular disorders." (PMID 40459864, 2025).
infection (1 paper, 2023). The state of being infected such as from the introduction of a foreign agent such as serum, vaccine, antigenic substance or organism. "For example, HYPK, which encodes a chaperone‐like protein associated with the regulation of cell death and apoptosis, and NPC2, which encodes a cholesterol transporter that is differentially expressed during disease infection, were detected as candidate genes under selection in the Northern region." (PMID 37780082, 2023).
HYPK also shares sentences with these, for which no sentence is quoted: neuromuscular disease (1 paper).